ITGAD (integrin subunit alpha D)
Description:
Integrin alpha-D/beta-2 is a receptor for ICAM3 and VCAM1. May play a role in the atherosclerotic process such as clearing lipoproteins from plaques and in phagocytosis of blood-borne pathogens, particulate matter, and senescent erythrocytes from the blood (Probable).
Synonyms: CD11d; ADB2
Tractability: Antibody: its Gene Ontology location is reachable by antibodies, with high confidence; UniProt predicts a signal peptide or a membrane-spanning region.
Gene: Protein-coding gene on chromosome 16 (31,393,335 to 31,426,505, forward strand). Ensembl gene ENSG00000156886.
Subcellular location: Cell membrane
Pathways (Reactome):
Extracellular matrix organization: Integrin cell surface interactions
Gene Ontology:
Molecular function: cell adhesion receptor activity; signaling receptor activity
Biological process: cell-cell adhesion mediated by integrin; heterotypic cell-cell adhesion; cell-cell adhesion; immune response; integrin-mediated signaling pathway; cell adhesion
Cellular component: integrin alphaD-beta2 complex; plasma membrane; cell surface; integrin complex
Genetic constraint (gnomAD): Loss-of-function variants: 100 observed, 137.38 expected, observed/expected ratio (o/e) 0.73, 90% interval 0.62 to 0.86. The upper end of that interval is the gene's LOEUF score, 0.86, which puts it in group 3 of 6, group 1 being the genes least tolerant of losing a copy. Missense variants: 1,333 observed, 1,491 expected, observed/expected ratio (o/e) 0.89, 90% interval 0.85 to 0.94. Synonymous variants: 558 observed, 599.01 expected, observed/expected ratio (o/e) 0.93, 90% interval 0.87 to 1.
Homologues: Orthologues: chimpanzee ITGAD (99% identical), guinea pig ITGAD (76% identical), pig ITGAD (76% identical), rat Itgad (74% identical), mouse Itgad (72% identical), rabbit ITGAD (68% identical), Drosophila melanogaster mew (21% identical), Caenorhabditis elegans ina-1 (20% identical), Drosophila melanogaster if (20% identical), Caenorhabditis elegans pat-2 (19% identical), Drosophila melanogaster scb (17% identical), Drosophila melanogaster ItgaPS4 (16% identical), and 1 more. Paralogues in human: ITGAX (65% identical), ITGAM (58% identical), ITGAL (31% identical), ITGA11 (29% identical), ITGAE (28% identical), ITGA10 (27% identical), ITGA2 (26% identical), ITGA1 (26% identical), ITGA4 (21% identical), ITGA9 (21% identical), ITGA5 (20% identical), ITGA8 (19% identical), and 5 more.
Diseases named in the same sentence as ITGAD in open-access papers:
ITGAD is named in the same sentence as 41 diseases in open-access papers, as found by Europe PMC text mining. Sharing a sentence is not in itself a finding about the gene and the disease. The quoted sentences say what the papers report.
gastric cancer (2 papers, 2015 to 2025). A primary or metastatic malignant neoplasm involving the stomach. "In the training cohort, a prognostic model for gastric cancer was developed using univariate and multivariate Cox regression analyses, along with stepwise regression, incorporating the genes SNCG, MNAT3, DDO, ITGAD, FGF8, and ABCB5." (PMID 41323282, 2025).
diabetes (1 paper, 2022). "ITGAD was also reported to have a low expression on neutrophils and monocytes in circulation, but upregulated on tissue macrophages, particularly in atherosclerotic lesions and adipose tissue during diabetes." (PMID 35038314, 2022).
endometrial adenocarcinoma (1 paper, 2022). "For the various functions of ITGAD in regulating biological progress, especially cell adhesion, we used the Ishikawa cell line, a well-differentiated human endometrial adenocarcinoma cell line and widely used as a model for investigation of endometrial function." (PMID 35038314, 2022).
Glanzmann thrombasthenia (1 paper, 2024). "Interestingly, VITT02 exhibited the presence of two variants in genes encoding for integrin family members, such as ITGA2B, encoding for the integrin alpha-IIb and associated with Glanzmann thrombasthenia (OMIM 273800), and ITGAD, encoding for the integrin alpha-D." (PMID 39035772, 2024).
intrauterine growth restriction (1 paper, 2022). "A microarray profiling in placenta tissues of preeclampsia and intrauterine growth restriction revealed that ITGAD was highly expressed and was associated with extracellular matrix organization." (PMID 35038314, 2022).
mucoepidermoid carcinoma (1 paper, 2020). A carcinoma morphologically characterized the presence of cuboidal mucous cells, goblet-like mucous cells, squamoid cells, cystic changes, and a fibrotic stromal formation. "The whole exon sequencing of 18 cases of mucoepidermoid carcinoma showed the occurrence of ITGAD gene mutation." (PMID 33335550, 2020).
cancer (4 papers, 2015 to 2025). A tumor composed of atypical neoplastic, often pleomorphic cells that invade other tissues. "Of note, consistent with the co-amplification profile of ITGAD, ITGAL, ITGAX, and ITGAM, we observed similar dysregulation patterns for them in cancers (belonging to one sub-cluster), validating our analytic pipeline." (PMID 39436262, 2024).
tumor (4 papers, 2020 to 2025). "After adjustment by tumor purity, we found ITGA1/A5/A8/A11/AD/AV and ITGB1 showed weakly correlation with macrophage markers in OC, ITGA5/A11 and ITGB5 weakly correlated with Treg markers, ITGAD and ITGB6 showed weakly correlation with natural killer cells markers." (PMID 32765584, 2020).
ITGAD also shares sentences with these, for which no sentence is quoted: atherosclerosis (4 papers); infection (4); acute respiratory distress syndrome (3); metabolic disease (3); B-cell lymphoma (2); Glucose intolerance (2); Hepatic steatosis (2); Insulin resistance (2); lipodystrophy (2); malaria (2); Anxiety (1); chronic gastritis (1); Cognitive impairment (1); concussion (1); COVID-19 (1); endometriosis (1); endothelial dysfunction (1); endotoxemia (1); hemangiosarcoma (1); histiocytic sarcoma (1); Hyperglycemia (1); injury (1); lupus (1); lymphoma (1); metastatic cancer (1); myocarditis (1); Obesity (1); ovarian carcinoma (1); parasitic infections (1); peritonitis (1).
A further 3 diseases each share a sentence with ITGAD in 1 paper.